KLF5 (KLF transcription factor 5)
Diseases named in the same sentence as KLF5 in open-access papers (continued):
Sharing a sentence is not in itself a finding about the gene and the disease.
cervical squamous cell carcinoma (1 paper, 2017). A squamous cell carcinoma arising from the cervical epithelium. "Notably, tumour necrosis factor (TNF)-α induced KLF5 expression by activating the p38 signalling pathway and high KLF5 and TNFRSF11a expression increased the risk of death in patients with cervical squamous cell carcinoma." (PMID 29146991, 2017). "In this study, we demonstrated that both TNFRSF11a and KLF5 were strongly expressed in HeLa and SiHa cells and human cervical squamous cell carcinoma (CSCC) tissues." (PMID 29146991, 2017).
chronic pancreatitis (1 paper, 2023). A chronic inflammatory process causing damage and fibrosis of the pancreatic parenchyma. "An inducible genetic model combining the deletion of Klf5 and the activation of KrasG12D mutant expression in pancreatic acinar cells together with chemically induced chronic pancreatitis was used." (PMID 38001687, 2023). "Human tissues originating from chronic pancreatitis patients showed increased levels of epithelial KLF5." (PMID 38001687, 2023).
dementia (1 paper, 2022). Loss of intellectual abilities interfering with an individual's social and occupational functions. "In the CSF samples, the KLF5 level slightly increased at the MCI stage, but it was higher in patients with AD–dementia (DAT) than in patients with normal cognition and MCI." (PMID 35883144, 2022).
developmental delay (1 paper, 2025). "Other candidate AD genes include DACH1, KCTD12, KLF5, and RBM26, all of which have been implicated in syndromic developmental delay, neuropsychiatric traits, or cancer predisposition based on case reports or CNV analyses." (PMID 40978814, 2025).
diabetic retinopathy (1 paper, 2024). "Prior research has demonstrated that KLF5 is closely associated with kidney diseases, such as hypertensive nephropathy and diabetic retinopathy." (PMID 38326870, 2024).
dysplasia (1 paper, 2013). A usually neoplastic transformation of the cell, associated with altered architectural tissue patterns. "Levels of KLF5 expression increased in parallel with advancing stages of neoplastic progression, being significantly elevated in gastritis, intestinal metaplasia, and dysplasia compared to normal gastric tissue." (PMID 23372710, 2013).
esophagitis (1 paper, 2019). An acute or chronic inflammatory disease affecting the esophageal wall. "Increased KLF5 expression was observed in BE tissues compared with that in normal esophageal and esophagitis tissues." (PMID 31632504, 2019). "Examination of KLF5 in patients with BE or esophagitis, and in healthy donors serving as controls, showed that the expression of KLF5 demonstrated a nuclear staining pattern at the site of BE glands." (PMID 31632504, 2019). "Results of immunohistochemistry studies performed to analyze the expression of KLF5, Cdx2, MUC2 and villin in the rat models showed a marked increase in nuclear staining in BE mucosa compared to that in normal esophageal and esophagitis mucosa." (PMID 31632504, 2019). "Similar to human tissue, the rat esophageal tissues showed stepwise increases in the expression of KLF5, Cdx2, MUC2 and villin in the order of normal esophageal, esophagitis and BE squamous epithelium based on immunohistochemical analysis." (PMID 31632504, 2019). "In both humans and rats, KLF5 was strongly expressed in BE esophageal squamous cells and was weakly expressed in esophagitis esophageal squamous cells, but no KLF5 expression was detected in normal esophageal squamous cells." (PMID 31632504, 2019).
fatty liver disease (1 paper, 2019). A reversible condition wherein large vacuoles of triglyceride fat accumulate in liver cells via the process of steatosis. "KLF5 has been associated to the onset of fatty liver disease, promoting hepatic lipid accumulation." (PMID 31036066, 2019).
intervertebral disc degeneration (1 paper, 2021). "KLF5 has also been shown to be associated with the inflammatory response in intervertebral disc degeneration, as it is involved in IL-1β-activated NF-κB cascade by enhancing p65 phosphorylation and p65 acetylation." (PMID 34551684, 2021).
intracranial aneurysm (1 paper, 2021). "Downregulation of KLF5 by miR-448-3p represses vascular wall thickening and macrophage infiltration and activation, which alleviates the pathogenesis of intracranial aneurysms." (PMID 33493334, 2021). "Upregulation of KLF5 reverses the function of miR-143/145 in VSMCs, thus promoting the expression of MMP2 and MMP3, as well as the growth and development of intracranial aneurysm." (PMID 33493334, 2021).
invasive ductal carcinoma (1 paper, 2022). "McNemar's consistency test showed that the consistency of HDAC1 and KLF5 expression in patients with invasive ductal carcinoma was statistically significant (kappa=0.287, P<0.001)." (PMID 35342356, 2022).
keratoconus (1 paper, 2021). A degenerative, structural disorder of the eye, characterized by a cone-shaped protrusion of the cornea. "We found evidence that SNPs associated with keratoconus often alter methylation of many genes, including LOX, PDDC1, SMAD3, HOXB1, KLF5, and BANP." (PMID 33649486, 2021). "For the first time, we have identified a substantial role for cell differentiation pathways and stem cell regulators such as KLF4 and KLF5 in the pathogenesis of keratoconus, and a role for genes influencing connective tissue maturity." (PMID 33649486, 2021).
kidney injury (1 paper, 2021). Trauma to the kidney. "As a result, KLF5 induced renal inflammation by promoting activation of pro‐inflammatory M1‐macrophages in UUO‐induced kidney injury." (PMID 33523554, 2021). "KLF5 promoted the activation of pro‐inflammatory M1‐macrophages in UUO‐induced kidney injury." (PMID 33523554, 2021). "In addition to KLF5’s role in modulating chronic kidney injury, KLF5 was also shown to regulate acute renal pathogenesis such as the nephritis." (PMID 33523554, 2021).
metastatic cancer (1 paper, 2021). A carcinoma which has spread from the original site of growth to another anatomic site. "Using our multi-omic data, we identified several enhancers that looped to the KLF5 promoter region in metastatic cancer cells (black arrows), which cannot be found in primary cancer cells." (PMID 34348759, 2021). "RNA-seq analysis revealed that KLF5 was significantly upregulated in metastatic cancer cells (adj." (PMID 34348759, 2021).
mucinous tumors of the ovary (1 paper, 2015). "This study provides a basis for understanding the diverse pathways targeted by somatic mutation in mucinous tumors of the ovary, although further functional work is required to elucidate the role of novel, less commonly affected genes with conflicting roles in the literature, such as ELF3 and KLF5." (PMID 26257827, 2015).
nasopharyngeal carcinoma (1 paper, 2022). A carcinoma arising from the nasopharyngeal epithelium. "In immunohistochemistry staining of KLF5, we found KLF5 protein expression was higher in nasopharyngeal carcinoma tissues in comparison to that of paired adjacent mucosa tissues." (PMID 35836107, 2022). "In addition, nasopharyngeal carcinoma and metastatic nasopharyngeal carcinoma tissues also had higher KLF5 expression levels than normal mucosa." (PMID 35836107, 2022). "In several human cancers, Krüppel-like factor 5 (KLF5), a zinc finger transcription factor, can contribute to both tumor progression or suppression; however, the precise role of KLF5 in nasopharyngeal carcinoma (NPC) remains poorly understood." (PMID 35836107, 2022).
nephrotic syndrome (1 paper, 2021). A collection of symptoms that include severe edema, proteinuria, and hypoalbuminemia; it is indicative of renal dysfunction. "KLF5 mRNA level decreased in the peripheral blood mononuclear cells from children with nephrotic syndrome as compared to control individuals." (PMID 33523554, 2021). "Additionally, KLF5 mRNA levels were decreased in the peripheral blood mononuclear cells from paediatric nephrotic syndrome patients compared with control individuals." (PMID 33523554, 2021).
osteoporosis (1 paper, 2023). A condition of reduced bone mass, with decreased cortical thickness and a decrease in the number and size of the trabeculae of cancellous bone (but normal chemical composition), resulting in increased fracture incidence. "In oxidative stress-induced osteoporosis, DNMT3B upregulates and triggers hypermethylation of KLF5 and reduces KLF5 expression, thus affecting β-catenin expression and its nuclear translocation, ultimately impairing osteogenesis in MSCs." (PMID 36950693, 2023).
pemphigus (1 paper, 2024). Pemphigus is a group of rare autoimmune diseases that cause blistering of the skin and mucous membranes (mouth, nose, throat, eyes, and genitals).This conditioncan occur at any age, but often strikes people in middle or older age. "Together, by addressing HDAC3 and KLF5, we present an option to modulate intercellular adhesion both under homeostatic conditions as well as in the pemphigus disease setting." (PMID 39271654, 2024). "Here we exploited HDAC3- and KLF5-dependent regulation of DSG3 transcription, which was identified by our screens, to rescue DSG3 protein levels and membrane localization in pemphigus models." (PMID 39271654, 2024).
pemphigus vulgaris (1 paper, 2024). Pemphigus is a group of chronic autoimmune skin diseases characterized by blister formations on the outer layer of the skin and the mucous membranes. "Together, KLF5 and histone deacetylase 3 are regulators of desmoglein 3 gene expression and intercellular adhesion and represent potential therapeutic targets in pemphigus vulgaris." (PMID 39271654, 2024). "Inhibiting histone deacetylase 3 increases KLF5 levels and protects against the deleterious effects of autoantibodies in murine and human pemphigus vulgaris models." (PMID 39271654, 2024). "Reduced levels of KLF5 in patient tissue indicate a role in pemphigus vulgaris." (PMID 39271654, 2024).
pinguecula (1 paper, 2021). A yellowish thickened lesion on the conjunctiva near the cornea representing a benign degenerative change in the conjunctiva caused by the leakage and deposition of certain blood proteins through the permeable capillaries near the limbus. "KLF5 and KLF7 encode transcription factors that oppose KLF4 activity; their expression did not change in pterygium or pinguecula." (PMID 34769520, 2021).
polyp (1 paper, 2023). A usually exophytic mass attached to the underlying tissue by a broad base or a thin stalk. "In addition, increased levels of KLF5 were observed in spontaneous hyperplastic intestinal polyp development and colonic tumorigenesis in Villin-Cre/LSL-KRASG12D mice, further supporting KLF5′s role as a mediator of the KRAS pathway in CRC formation." (PMID 37173904, 2023).
prostate (1 paper, 2023).
prostate adenocarcinoma (1 paper, 2020). "In the TCGA provisional prostate adenocarcinoma dataset, KLF5 mRNA levels co-expressed with that of BCL2 with Pearson co-efficient value equal to 0.49 (p-value < 0.0001), which indicates an intermediate correlation." (PMID 32685011, 2020).
pulmonary fibrosis (1 paper, 2021). Chronic progressive interstitial lung disorder characterized by the replacement of the lung tissue by connective tissue, leading to progressive dyspnea, respiratory failure, or right heart failure. "Moreover, bleomycin‐induced lung fibrosis was exacerbated in Klf5+/− mice when compared to wild‐type." (PMID 33523554, 2021).
pulmonary hypertension (1 paper, 2011). Increased pressure within the pulmonary circulation due to lung or heart disorder. "Our results indicate that levels of KLF5 correlate with the severity of PAH in humans and experimental pulmonary hypertension." (PMID 21951574, 2011).
rectal adenocarcinoma (1 paper, 2021). "Taking KLF5 as an example, the related pathway of KLF5 coexpressed genes in rectal adenocarcinoma was analyzed." (PMID 34367275, 2021). "We used UALCAN to study which genes in rectal adenocarcinoma are related to the expression of KLF4 or KLF5." (PMID 34367275, 2021). "The data on genes coexpressed with KLF5 in rectal adenocarcinoma were downloaded and applied GO analysis on this data." (PMID 34367275, 2021). "However, our results indicated that patients with high expression of KLF5 in rectal adenocarcinoma have a higher survival rate." (PMID 34367275, 2021).
reovirus infection (1 paper, 2018). "Transcripts that were up-regulated and stabilized following reovirus infection included SMAD 1, 2, 6 &7, Tgif, c-Myc, CITED2 and KLF5, which encode components of the SSN that control transcription of genes that regulate apoptosis and cell growth." (PMID 30261045, 2018).
skin cancer (1 paper, 2022). "Thus, multiple signal pathways, such as BRAF, PI3K, and TP63/KLF5, can control SREBP-1 for the regulation of skin cancer progression." (PMID 35912181, 2022).
small cell lung carcinoma (1 paper, 2021). Small cell lung cancer (SCLC) is a highly aggressive malignant neoplasm, accounting for 10-15% of lung cancer cases, characterized byrapid growth, and early metastasis. "The data exhibited that the expression of KLF5 was almost similar in 4–5 malignant tumor samples, while that of POU2F2 was upregulated only in small cell lung cancer samples." (PMID 34722892, 2021).
small intestine tumors (1 paper, 2021). "More importantly, in ApcMin/KRAS V12 double transgenic mice that had a great tendency to develop small intestine tumors, deleting one allele of Klf5 led to a 92% reduction in tumor burden." (PMID 33923166, 2021).
tauopathies (1 paper, 2022). "Thus, to discriminate the two tauopathies, we hereby propose JUN(B,D)HIGH, FOS(L1,L2)HIGH as well as the involvement of DUX4, KLF5, MAX::MYC, PAX6, and PPARG to support the identity of CBD-originated astrocytes." (PMID 35976433, 2022).
Treacher-Collins syndrome (1 paper, 2025). A congenital disorder of craniofacial development characterized by bilateral symmetrical oto-mandibular dysplasia without abnormalities of the extremities, and associated with several head and neck defects. "The conserved role of klf5 across species suggests that insights from zebrafish could inform studies of craniofacial disorders in humans, where FGF signaling disruptions are implicated in conditions like Pierre Robin sequence and Treacher Collins syndrome." (PMID 41303527, 2025).
tuberculosis (1 paper, 2024). A chronic, recurrent infection caused by the bacterium Mycobacterium tuberculosis.
Ventricular arrhythmia (1 paper, 2025). "Our in vivo experiments revealed that transplantation of KLF5-overexpressing BMSCs in mice with MI led to a substantial reduction in ventricular fibrosis and the occurrence of ventricular arrhythmias (VAs)." (PMID 40822849, 2025). "Our objective was to investigate the role of miR-152-3p, regulated by KLF5 in BMSCs, which may potentially aid in alleviating advanced ventricular arrhythmias (VAs) following MI by inhibiting the transition of CFs to CMFs." (PMID 40822849, 2025).
ventricular tachycardia (1 paper, 2025). A disorder characterized by an electrocardiographic finding of three or more consecutive complexes of ventricular origin with a rate greater than a certain threshold (100 or 120 beats per minute are commonly used). "The results showed that the transplantation of KLF5-BMSCs led to a significant reduction in the occurrence time of PVCs, VB, (VT1), and ventricular tachycardia (VT2), and its score was significantly lower than that of MI mice and NC-BMSCs transplantation mice." (PMID 40822849, 2025).
viral infection (1 paper, 2011). "Thus, KLF5 upregulation can be caused by many diverse conditions that lead to PAH in addition to hypoxia, including growth factors, vasoactive molecules, or viral infection of PASMC." (PMID 21951574, 2011).